NOTCH1 (notch receptor 1)
Diseases named in the same sentence as NOTCH1 in open-access papers (continued):
Sharing a sentence is not in itself a finding about the gene and the disease.
breast cancer (continued). "Studies in the human breast cancer cell lines MCF7 and MDA-MB-231 show that NOTCH1 or NOTCH4 silencing reduces tumorsphere formation and inhibits tumor growth in vivo; however, NOTCH4 suppression appears to have the greatest inhibitory effect." (PMID 22992387, 2012). "For example, down-regulation of Notch-1 signaling pathway increased chemosensitivity to several chemotherapeutic drugs such as taxotere, doxorubicin, and tamoxifen, indicating that Notch signaling pathway could be a novel target for overcoming drug-resistance in breast cancer." (PMID 22949821, 2012). "Thus, Notch1 and Znf143 may co-regulate Nanog expression in mammary tumor-initiating cells." (PMID 22992387, 2012). "Taken together, the results from this study demonstrate for the first time that Notch-1 and Notch-4 are novel transcriptional targets of PEA3 in breast cancer cells." (PMID 21679465, 2011). "E2 promoted 8-fold and 6-fold increase in Notch1 and JAG1 expression, respectively, in breast cancer MCF-7 cells." (PMID 21731759, 2011). "Our investigations are the first to show that PEA3 is a transcriptional activator of Notch-1 and Notch-4 in MDA-MB-231 breast cancer cells, an example of triple-negative breast cancer." (PMID 21679465, 2011). "Western blot analysis showed that both NOTCH1 and NOTCH2 were expressed at different degrees in six human breast cancer cell lines." (PMID 20010940, 2010). "Notch1 and Notch4 were identified as mouse mammary tumour virus (MMTV) integration sites in murine mammary tumours." (PMID 20010940, 2010). "Furthermore, we detected cleaved Notch1 and Hes1/5 in early precursors of breast cancers - hyperplasia and ductal carcinoma in situ - suggesting that aberrant Notch activation may be an early event in breast cancer progression." (PMID 20030805, 2009). "Increased NOTCH1 and NOTCH4 expressions have been observed in breast cancer." (PMID 41561443, 2026). "Notch 2’s role in breast cancer is not as well understood as Notch 1, but has been known to impact cell fate decisions and differentiation in the mammary gland." (PMID 37726449, 2024). "Notably, absence of the PEST domain and inactivation of FBW7 are common mechanisms for strong gain-of-function in NOTCH1 in human cancers such as T-ALL, breast cancer, and adenoid cystic carcinoma." (PMID 38043798, 2024). "Similarly, CXCL2 activated the Notch1/Hey1 signalling pathway in breast cancer cells, leading to an increase in ALDH+ breast cancer stem cells." (PMID 39523215, 2024). "We used a real-time transcriptional activity assay known as TRACER (TRanscriptional Activity CELL aRray) to measure the dynamic activity of six transcription factors involved in EMT signaling specific for breast cancer (TWIST1, SNAIL, HIF1a, RUNX1, RUNX2, and NOTCH1)." (PMID 38398186, 2024). "Furthermore, we identified additional breast cancer genes deleted more frequently in warm/hot tumors than in cold tumors (BAP1, PBRM1, NOTCH1, CCND1, RB1)." (PMID 38714665, 2024). "For example, STK38 increases NOTCH1 (notch receptor 1) signaling activity by impairing Fbw7 (F-box and WD repeat domain-containing 7) mediated the degradation of NICD (notch intracellular domain) to enhance breast cancer stem cell properties." (PMID 37046714, 2023). "In addition, not only STAT3 but also the NOTCH1 signaling pathway is known to be involved in the acquisition of chemotherapy resistance in head and neck squamous cell carcinoma (HNSCC), breast cancer, and gastrointestinal cancer." (PMID 37373457, 2023). "Notch1 and Notch4 can drive cell cycle progression in the absence of estrogen in ERα-positive breast cancer cells and induce the expression of cyclins A and B." (PMID 37568775, 2023).
breast cancer (continued). "Indeed, genetic or pharmacologic inhibition of Notch1 enhanced trastuzumab (an anti-HER2 therapy) sensitivity and diminished recurrence from residual dormant breast cancer cells after trastuzumab treatment." (PMID 37440925, 2023). "In breast cancer cells, ATO may be included not only in Notch-1 but also in other oncogenic signaling pathways." (PMID 36619302, 2022). "EZH2 enhances breast cancer initiation by directly binding to the NOTCH1 promoter and activates NOTCH1 signaling independent of its catalytic H3K27me3 activity." (PMID 36313363, 2022). "In breast cancer cells, ATO may be included in Notch-1, PIN1, and kinases oncogenic signaling pathways." (PMID 36619302, 2022). "Another study reports that in breast cancer cells, expression of the miR-106b-93-25 cluster results in NEDD4L down regulation and subsequent stabilization of Notch1, a direct target of NEDD4L ubiquitination; Notch1 is generally overexpressed in GBM and is linked to lower overall survival." (PMID 36552827, 2022). "Importantly, emerging evidence suggests that Notch1 signaling mediates cancer cell invasion and metastasis by inducing EMT through the upregulation of Slug, which is involved in breast cancer metastasis in vitro and in vivo." (PMID 35457181, 2022). "Our results revealed a significant upregulation of cleaved, active Notch1 intracellular domain (N1ICD) and canonical Notch1target HES1 in adjacent breast cancer cells (Co-MCF-7-mRFP) of SEN-MCF-7, compared with that in MCF-7-mRFP cultured with senescence culture medium (SEN-CM-MCF-7-mRFP)." (PMID 33467780, 2021). "Thus, our data suggest that in the context of hormone-dependent breast cancer, PIM-mediated phosphorylation of Notch3 promotes tumor growth but via a different mechanism than phosphorylation of Notch1." (PMID 33775697, 2021). "Additionally, NOTCH signaling drives metastasis in numerous cancers and Pin1 prevents NOTCH1 and NOTCH4 from undergoing FBXW7-mediated degradation, leading to an increase in breast cancer stem cells’ (CSCs) self-renewal and metastasis." (PMID 33807199, 2021). "Further analysis of mutual exclusivity showed that only one gene pair (NOTCH1-RELA) exhibited significant co-occurrence (p < 0.05) in the breast cancer study by the INSERM 2016 project, which indicated the pivotal role of NOTCH1 and RELA under tangeretin treatment." (PMID 34335799, 2021). "However, growth of human breast cancer (HCC2218 and HCC1599) and T-ALL cells, expressing a ligand-independent Notch1 (membrane-tethered, active Notch), is inhibited by Bafilomycin A1 or γ-secretase inhibitors." (PMID 34572582, 2021). "Indeed, the addition of GSI or monoclonal antibodies against the NRR of Notch1 to docetaxel attenuated the CSC pool and sensitized cells to the chemotherapeutic treatment in experimental models of prostate cancer, breast cancer, NSCLC, and HNSCC." (PMID 34680255, 2021). "In addition, we found that miR-378 expression was positively correlated with β-catenin, NOTCH1 and EZH2 expression in breast cancer based on the TCGA database (n = 470) (p < 0.001)." (PMID 33823894, 2021). "For example, in the work of Valcourt and Day, PLGA NPs functionalized with Notch1 antibodies were employed for the specific delivery of miR-34a into triple-negative breast cells (TNBC), an aggressive type of breast cancer, unsusceptible to current targeted or hormonal therapies." (PMID 34834316, 2021). "In contrast to Notch1 and 4, our previous study showed that Notch3 was mainly expressed in luminal breast cancer cells but not in either basal-like or HER2 (human epidermal growth factor receptor 2)-positive breast cancer cell line." (PMID 32636747, 2020). "Moreover, the miR‐106b‐25 cluster mediated oncogenesis in breast cancer by activation of NOTCH1 by targeting NEDD4L in both ER+ and TNBC breast cancer cells, suggesting that the miR‐106b‐25/NEDD4L/NOTCH1 axis played a crucial role in breast cancer." (PMID 32249490, 2020).
breast cancer (continued). "Clementz and colleagues (2011) demonstrated NOTCH1 and NOTCH4 are transcriptionally activated by PEA3 in breast cancer cell lines, and knockdown of PEA3 or treatment with a GSI resulted in a G1 cell cycle arrest, increased apoptosis, and either treatment reduced tumor burden in mice." (PMID 33003540, 2020). "Downregulation of Notch3 but not Notch1 considerably suppressed proliferation and induced apoptosis of the Erbb2-negative breast cancer cell lines implicating Notch3-mediated signaling in the proliferation of these cells." (PMID 32211044, 2020). "Consistently, analysis of human breast cancer tissue demonstrates NOTCH1 is highly expressed in TNBCs, and the activated form of NOTCH1 correlates positively with increased phosphorylation of ATR." (PMID 32591500, 2020). "Thus, disruption of this microenvironmental juxtacrine/angiocrine loop at any level—such as Notch1 and VEGFA—severely diminishes the aggressiveness of breast cancer in vitro and in vivo." (PMID 33046710, 2020). "Moreover, under BRCA1-defective conditions, NOTCH1 tended to display an enhanced ability to promote TNBC and basal-type breast cancer." (PMID 32591500, 2020). "As we have expected, miR-34a high expression tumors demonstrated lower expression levels of EMT inducing factor, Notch-1, in whole METABRIC cohorts, as well as in all the subtypes of breast cancer patients (p < 0.001, p < 0.001, p < 0.05, and p < 0.01, respectively)." (PMID 32357442, 2020). "Notch genes (Notch1 and Notch4), when expressed under the control of whey acidic protein (WAP) or mouse mammary tumor virus (MMTV) promoters in the mouse, result in the formation of mammary carcinoma." (PMID 32391382, 2020). "In particular, Kim and colleagues revealed that treatment of MCF-7, MDA-MB-231, and SUM159 human breast cancer cells with Benzyl isothiocyanate (BITC), a constituent of cruciferous vegetables, increases levels of the active form of Notch1, Notch2, and Notch4 in both cultured and xenografted cells." (PMID 31379945, 2019). "Moreover, in breast cancer cells with high levels of PIN1, NOTCH1 signaling is strongly activated despite presence of FBXW7, inciting expansion of breast cancer stem cells (CSC) and tumorigenesis." (PMID 30873382, 2019). "Notably, the crosstalk between the Notch-1, Wnt/β-catenin, and STAT3 signaling pathways has been reported in breast cancers and breast cancer stem cells." (PMID 31357721, 2019). "Additionally, inhibition of the Akt and Notch1 signaling pathways abrogated Nanog-mediated ALDH activity and radioresistance of breast cancer cells." (PMID 30845764, 2019). "In breast cancer, S100A16 upregulation could promote epithelial-mesenchymal transition (EMT) via the Notch1 pathway, thereby enhancing cancer cell invasion." (PMID 29746588, 2018). "High expression of Notch1 and JAG1 correlate with poor prognosis in lung and breast cancer." (PMID 30004402, 2018). "Gain-of-function mutations in NOTCH1 and NOTCH2 are found in breast cancer, and NOTCH1 translocations are also found in ductal carcinoma in situ (DCIS), which may be considered an early stage in breast cancer development." (PMID 30388742, 2018). "Consistent with our model, both Notch1 and IKKα (CHUK) mRNA expression are strongly associated with poor survival in TNBC but not ER+ breast cancers." (PMID 30564555, 2018). "Although a direct link with notch-4 has not been described, GPER has been shown to engage notch-1 signaling to alter gene expression and cell migration in breast cancer in vitro." (PMID 29899833, 2018). "In line with this, ectopic Notch1 ICD expression, which results in high levels of Notch signaling activation, increased normoxic HIF2α protein in primary breast cancer cells, human medulloblastoma cell lines D324 and DAOY, as well as the VHL-deficient 786-O renal carcinoma cell line." (PMID 29993038, 2018).
breast cancer (continued). "Another study showed that ErbB-2 inhibition by a monoclonal antibody Trastuzumab activated Notch1 in breast cancer cell lines and Trastuzumab-resistant cells showed higher Notch activity." (PMID 30061899, 2018). "In breast cancer stem cells, high levels of prolyl-isomerase Pin1 sustain Notch signaling protecting Notch1 and Notch4 from proteasomal degradation." (PMID 30478302, 2018). "MiR-34a may participate in the regulation of drug-resistant breast cancer by targeting BCL-2, CCND1, and NOTCH1." (PMID 29290947, 2017). "Furthermore, NOTCH1 has been identified as a mediator of the RAS oncogenic pathway; this is often deregulated during the early stages of breast cancers and participates in the JAG1/NOTCH1/CCND1 axis critical for maintaining proliferation of TN BC cells." (PMID 27888801, 2017). "In other words, miR-34a may participate in the regulation of multidrug resistance in breast cancer by down-regulating the expression of BCL-2, CCND1 and NOTCH1." (PMID 29290947, 2017). "Importantly, there was a connection between the high level of Notch1 and the HER-2 molecular subtype of breast cancer." (PMID 29104587, 2017). "This indicated that miR-34a is involved in the regulation of drug-resistant breast cancer and may target BCL-2, CCND1, and NOTCH1." (PMID 29290947, 2017). "Altogether, our findings suggest that miR-34a is an MDR and prognosis indicator of breast cancer, which may participate in the regulation of drug-resistant breast cancer by targeting BCL-2, CCND1, and NOTCH1." (PMID 29290947, 2017). "It has been shown that NOTCH1 has been overexpressed in the patients with breast cancer, but no study has investigated the expression of NOTCH1 and its correlation with other molecular and hormonal markers of breast cancer so far." (PMID 28330128, 2016). "Similar to NUMB, the EMT negative regulators GATA3 and FOXA1 had significantly lower expression in the BLBC subtypes and in ER-negative and higher histological grade breast cancer patients, whereas the EMT inducers FOXC1, FOXC2 and SNAI1 mimicked the expression profile of Notch1." (PMID 27506933, 2016). "Using two different antibodies recognizing the extracellular and the intracellular domain of Notch1, as well as the supernatant from the human breast cancer cell lines (MDA-MB-231) as control, we observed that Notch1 is present in CSF and cellular supernatant in various forms." (PMID 27364742, 2016). "Yet, a clear understanding of the role of NOTCH1 as a prognostic marker in different breast cancer types is still lacking." (PMID 28330128, 2016). "We therefore hypothesized that, in total contrast to Notch1, Notch3 may act to inhibit EMT in breast cancer epithelial cells." (PMID 27841855, 2016). "Similar to NUMB, the EMT negative regulators GATA3 and FOXA1 had significantly lower expression in the BLBC subtypes, ER-negative and higher histological grade breast cancer patients, while the EMT inducers FOXC1, FOXC2 and SNAI1 mimicked the expression profiles of Notch1." (PMID 27506933, 2016). "The impact of Notch1 silencing by specific shRNAs on the EMT and invasion of human breast cancer MCF-7 and MDA-MB-231 cells as well as xenografts was tested by western blot, real-time polymerase chain reaction (RT-PCR), immunofluorescence, transwell, and immunohistochemistry assays." (PMID 25645291, 2015). "To investigate whether Notch signaling regulates the EMT process in breast cancer cells, we established stable Notch1-shRNA-transfected cells (MCF-7-shNotch1 cells and MDA-MB-231-shNotch1 cells) to inhibit Notch1 expression." (PMID 25645291, 2015). "The Notch1 intracellular domain (N1ICD) and Jagged1 were expressed in breast cancer cells." (PMID 25645291, 2015). "The significance of different isoforms of Notch in breast cancer is not clear, however, Notch1 is believed to be essential." (PMID 26121683, 2015).
breast cancer (continued). "Immunocytochemistry results clearly show that Notch1 translocation from the cell membrane to the nucleus upon activation by EDTA treatment, indicative of the function of the canonical Notch signaling in NSCLC and breast cancer cells." (PMID 25653136, 2015). "Taken together, our data showed that Notch1 knockdown leads to the mesenchymal–epithelial transition (MET) process, whereas Jagged1-induced Notch signaling activation promotes the EMT process in breast cancer cells." (PMID 25645291, 2015). "In addition, the Notch1–Slug axis was shown to be vital for the Jagged1-induced promotion of EMT and invasion in breast cancer." (PMID 25645291, 2015). "Notch-1, -3, or -4 have shown oncogenic activity in T cell acute lymphoblastic leukemia (T-ALL), B-cell lymphoma, cervical, colon, lung, and ovarian cancers while, surprisingly, Notch-2 has displayed tumor suppressive activity in some breast cancer subtypes." (PMID 25566499, 2014). "Overexpression of receptor Notch-1, or its ligand Jagged-1, has been shown to predict poor survival of breast cancer patients, suggesting a significant role of the Notch pathway in this malignant disease." (PMID 26932376, 2014). "All of these results first indicated that Notch1 was the upstream of ZEB and may play an important role in triggering EMT in breast cancer cells." (PMID 25287362, 2014). "All the results together, the SIRT1 protein and Notch1 signaling mainly manifested in the level of N1IC played an important role in the prognosis of patients, and may represent therapeutic targets for breast cancer." (PMID 25420528, 2014). "Visfatin induced Notch1 expression in MDA-MB-231 breast cancer cell line and in nontransformed MCF10A mammary epithelial cells, whereas visfatin depletion reduced Notch1 mRNA and protein levels." (PMID 24970818, 2014). "Furthermore, LLL12 inhibited Twist1, Notch-1, and Notch-3 expression in ALDH+ breast cancer stem-like cells, which have recently been reported as STAT3 or Interleukin-6 target genes." (PMID 24376586, 2013). "Activating deletions in either NOTCH1 or NOTCH2 have been identified in a minority of breast cancers, most of which are triple-negative (ER/PR/HER2 negative) tumors." (PMID 23825651, 2013). "Analysis of CD24 and CD29 surface-marker expression on the lineage-negative population of NOTCH1 mammary tumor cells revealed expression of a luminal cell profile (Lin-CD24+CD29lo), compared with wild-type mammary cells." (PMID 22992387, 2012). "To determine whether mammary tumor growth/survival remains NOTCH1 dependent, we established cell lines from primary MMTV-tTA/TOP-ICN1 mammary tumors." (PMID 22992387, 2012). "The reason we selected SKBR-3 cell line for further study is that these cells have a higher expression, but not the highest, of Notch-1 in multiple breast cancer cell lines." (PMID 22949821, 2012). "PEA3 activates Notch-1 transcription in MCF-7, MDA-MB-231 and SKBr3 breast cancer cells." (PMID 21679465, 2011). "Furthermore, a recent clinical study reported that the expression level of Notch1, Notch3, and JAG-1, one of the Notch ligands, were inversely correlated with the overall clinical outcomes in breast cancer patients." (PMID 19660128, 2009). "In basal-like and HER2-positive breast cancers, we demonstrated that a low WWOX/HIF1A ratio is particularly detrimental, as it triggers HIF1α-mediated upregulation of immunosuppressive mediators such as TLR4, NOTCH1, PTX3, and IL6R, alongside glycolytic enzymes like GLUT1 and HK2." (PMID 41007296, 2025). "In breast cancer, stem cells are characterized by the expression of membrane molecules CD24 and CD44 as well as by the expression of EMT proteins and transcription factors, for instance, neurogenic locus notch homolog protein 1 (NOTCH1) and octamer-binding transcription factor 4 (OCT4)." (PMID 36980680, 2023).